CCL2 (C-C motif chemokine ligand 2)
Diseases named in the same sentence as CCL2 in open-access papers (continued):
Sharing a sentence is not in itself a finding about the gene and the disease.
tumor (continued). "TAAs release CC-chemokine ligand 2 (CCL2), through which they cause immunosuppression and further recruit factors into the tumour microenvironment to facilitate tumour survival and propagation." (PMID 36678741, 2022). "Considering the chemotactic effect of CCL2 on monocytes, recent research has found that CCL2 is involved in the cross-talk between tumor cells and tumor-associated macrophages (TAMs) in the tumor microenvironment." (PMID 36403055, 2022). "The CCL2/CCR2 signaling pathway was implicated in the migration of MDSC to tumor in vitro and in vivo." (PMID 35267547, 2022). "CCL2-mediated TAM infiltration is linked to increased inflammation, angiogenesis, and tumorigenesis; therefore, anti-CCL2 immunotherapy has the potential to reduce tumor burden and recurrence risk." (PMID 35461243, 2022). "GBM cells are the main producers of CCL2 and an increase of CCL2 expression is associated with major infiltration by monocytes in tumor bearing-mice." (PMID 36048342, 2022). "Chemokines secreted by tumor cells, such as C-C Motif Chemokine Ligand 2, C-C Motif Chemokine Ligand 5, and colony stimulating factor 1, can recruit M2-type tumor-associated macrophages, and their abundance in TME correlates with a poor prognosis." (PMID 35720039, 2022). "A study showed that CREBBP/EP300 mutation in DLBCL patients had higher CCL2 expression, and tumor progression was induced by TAMs throughout the FBXW7-NOTCH-CCL2/CSF1 axis." (PMID 36578079, 2022). "In C57BL/6 healthy mice, the plasma concentration of CCL2 was diminished in the deficiency group as compared to the control group, and a similar tendency was preserved in E0771 tumor-bearing mice (p = 0.0779)." (PMID 36230508, 2022). "It was found that irradiation of the tumor caused a significant increase in CCL2 production and radiation-dependent recruitment of monocytes/macrophages." (PMID 36249052, 2022). "In several cancers, such as ovarian, breast, glioblastoma, squamous cell carcinoma (SCC), and NSCLC, CCL2 expression positively correlated with increased infiltration of tumor-associated macrophages (TAMs)." (PMID 34503058, 2021). "This chemokine has been previously involved in tumor promotion under obese condition and elevated circulating CCL2 levels have been associated with bone metastasis in prostate cancer patients." (PMID 34639088, 2021). "In a previous report, we revealed that the nitration of the CCL2 chemokine, caused by the oxidative overload within the tumor mass, impacted on immune cell trafficking by selectively affecting anti-tumoral T cell infiltration." (PMID 34675917, 2021). "Chemokines have been implicated in developing and maintaining pain, and CCL2 immunoreactivity was found in animals bearing a tumor." (PMID 34575835, 2021). "Protein kinase C (PKC), an important intracellular signalling mediator, is known to upregulate CCL2 secretion and is associated with tumour cell invasion." (PMID 34464477, 2021). "Tumor-associated M2 polarized macrophages (TAMs) promote tumor cell to bone metastasis through CCL2/CCR2 or colony-stimulating factor 1 (CSF1)/CSF1R signaling." (PMID 34831167, 2021). "CCL2 is an inflammatory chemokine that promotes the recruitment of Tumor-associated macrophages (TAMs) to tumor sites." (PMID 34733886, 2021). "CCL2 circulating levels were associated with tumor presence and with the abundance of Fusobacterium nucleatum, Bacteroides fragilis and Gemella haemolysans." (PMID 34639088, 2021). "In agreement to our data, several chemokines, among which was CCL2, have been previously associated with increased tumor growth and progression." (PMID 34639088, 2021). "While IL-8 and VEGF are known stimulators of angiogenesis, CCL2/MCP-1 has been demonstrated to promote the recruitment of anti-inflammatory tumor-associated macrophages." (PMID 33287630, 2021).
tumor (continued). "In a metastatic prostate cancer model, combined treatment with an anti‐CCL2 antibody and docetaxel caused reduced tumor burden and bone resorption, as well as an improved survival period." (PMID 33463063, 2021). "Tumour‐associated macrophages (TAMs) recruited by CCL2 upregulated the expression of angiogenic factors such as VEGF." (PMID 34464477, 2021). "CCL2 is associated with both tumor-promoting and tumor-suppressing activities, activating pro-tumor macrophages and enhancing anti-tumor neutrophil activity." (PMID 34183723, 2021). "In BCa, tumor cells are implicated in macrophage recruitment via the secretion of CCL2 and MIF/CXCL2." (PMID 34572939, 2021). "The involvement of CCL2 in the recruitment of CCR2-bearing tumor-associated macrophages (TAMs), which play critical roles in tumor vascularization and development, has been widely explored." (PMID 34943797, 2021). "The CCL2 (monocyte chemoattractant protein-1 [MCP-1])/CCR2 axis is implicated in the recruitment of myeloid cells to the tumor sites." (PMID 35008305, 2021). "Tumor-associated macrophages (TAMs) accumulate at the tumor site, as well as circulating monocytes, recruited by the tumor-derived chemotactic factor, CCL2." (PMID 34177887, 2021). "In humans, expression of CCL2 is highly elevated during tumor development, and is associated with infiltration of macrophages." (PMID 34771552, 2021). "We found a dramatic decrease of TAMs numbers and F4/80 mRNA expression in the CCL2 deficient tumor area compared with control." (PMID 34580284, 2021). "In HCC mice, Drp1 overexpression caused mtDNA stress, promoting Ccl2 secretion and the infiltration of tumor-associated macrophages (TAMs)." (PMID 33920670, 2021). "These protein levels were significantly higher in TANs than in the peripheral blood, and the number of CCL2+ or CCL17+ TANs was associated with tumor size, microvascular invasion, differentiation, and clinical stage." (PMID 34071550, 2021). "IL-1β-deficient tumor-bearing mice were shown to have lower levels of CCL2 in tumor tissue, which resulted in decreased macrophage infiltration and CD11b+ dendritic cell maturation." (PMID 34386431, 2021). "In general, the elevated expression of CCL2 by BC cells is associated with an aggressively metastasizing tumor phenotype and with poor prognoses in patients." (PMID 34239022, 2021). "We showed that tumors expressing a deleted form of HIF-1α displayed increased levels of NK and CD8+ effector T cells in the tumor microenvironment, which was associated with high levels of CCL2 and CCL5 chemokines." (PMID 34155342, 2021). "RT-induced Ccl2 expressions in lungs were already linked to the recruitment of myeloid cells with reported tumor-promoting activities." (PMID 34209135, 2021). "High CCL2 expression positively correlates with increased infiltration of tumor associated macrophages and predicts worse prognosis in multiple human and murine cancers." (PMID 34164400, 2021). "Meanwhile, decreased expression of CCL2 and CCL7 was detected in the experimental group, and the expression of CCL2 is closely associated with tumor angiogenesis and high invasiveness, while CCL7 has a recruitment effect on Treg." (PMID 35095931, 2021). "Administration of a CCR2 antagonist or the loss of CCL2 expression in tumor cells enhances antitumor immunity in the residual tumor and overcomes the resistance to ICB therapy." (PMID 35003065, 2021). "Elevated expression levels of CCL2 were found to be correlated with tumor-associated macrophage accumulation, and both factors conveyed a poor prognosis in esophageal carcinogenesis." (PMID 34869345, 2021). "For instance, X. Jia’s group found that CCL2 in ESCC prompts the recruitment of tumour-associated macrophages and induces immune escape through PD-1 signalling." (PMID 33869274, 2021). "In HCC, tumor-associated neutrophils combined with CCL2 and CCL17 promote the growth, progression, and resistance to sorafenib." (PMID 33568167, 2021).
tumor (continued). "The tumor-derived chemokines implicated in TAM recruitment in BCa include CCL2, SDF-1 and the ligands of CXCR2." (PMID 34572939, 2021). "CCL2 promotes recruitment of MDSCs and tumor-associated macrophages (TAMs) that create an immunosuppressed tumor microenvironment and favor bone colonization in prostate cancer." (PMID 32929562, 2021). "C5a, sCb-9, and CCL2 were measured at endpoint of the study (14 days) in the sera of tumour-bearing properdin-deficient and wildtype and were found to be significantly decreased in the deficient animals." (PMID 33494138, 2021). "Newly recruited monocytes via CCR2 and CCL2 (also known as monocyte chemoattractant protein-1 (MCP-1)) signaling become motile tumor associated macrophages (TAMs) and later develop into sessile perivascular macrophages." (PMID 33096815, 2020). "CCL2 is a major chemokine involved in attracting bone-marrow-derived mesenchymal cells to the tumor microenvironment, and CCL2 loss decreases accumulation of these cells." (PMID 32943658, 2020). "CCL2-CCR2 signaling is key during TAM recruitment to the tumor microenvironment; therefore, inhibition of CCL2 has been associated with reduced tumor progression in different cancer models, including bone." (PMID 32326073, 2020). "Recently, our colleagues uncovered that neddylation inactivation in tumor cell increased C‐C motif chemokine ligand 2 (CCL2) secretion and then promoted tumor‐associated macrophage infiltration." (PMID 32749072, 2020). "Evidence supporting this notion comes from a study of ovarian cancer patients in which both tumor cells and tumor‐associated macrophages were found to secrete the chemokine CCL2." (PMID 33067808, 2020). "Under the influence of factors released by cancer cells, such as chemokine CCL2, peripheral monocytes and local macrophages are recruited to the primary tumor and transformed into tumor-associated macrophages (TAMs)." (PMID 33238581, 2020). "The direct or indirect induction of proinflammatory mediators, like IFNγ, IL4, IL6, IL13, VEGF, GM-CSF, CSF-1, Ang-2, CCL2 and other chemokines in the tumor milieu, has an antitumor effect linked to M1 polarization of TAM." (PMID 32708142, 2020). "Increased expression of CCL2 in a tumor is associated with a worse prognosis for patients with solid tumors." (PMID 33182504, 2020). "Several studies have also demonstrated that serum CCL2 was elevated and associated with tumor stage in patients with breast, ovarian, and lung cancers." (PMID 32471499, 2020). "Deficiency of CCL2 in stromal cells like macrophages reduces infiltration of macrophages, angiogenesis, early tumor necrosis and lung metastasis in the 4T1 breast tumor model." (PMID 32219066, 2020). "CCL2 production in tumors facilitates the accumulation of immune-suppressive tumor-promoting/tumor-associated macrophages, but CCL2 can also activate monocytes for tumor cell killing." (PMID 32429318, 2020). "CCL2 can also promote cancer progression indirectly through increasing the recruitment of tumor-associated macrophages into the tumor microenvironment." (PMID 33297571, 2020). "CCL2 is relevant as it has been shown to recruit monocytes into the primary tumor, where they can differentiate into tumor-associated macrophages (TAMs)." (PMID 32455980, 2020). "Our previous study suggested the involvement of CCL2 and tumor associated macrophages (TAMs) in esophageal carcinogenesis." (PMID 32103760, 2020). "CCL2, produced by tumor cells and associated stromal cells, is one of the best characterized tumor-derived factors that induces chemotaxis in monocytes, causing circulating monocytes to be recruited from the peripheral blood into the tumor sites." (PMID 32824016, 2020). "CCL2 overexpression has been associated with poor patient prognosis in various tumor types, including BC." (PMID 33213491, 2020). "The chemokine CCL2 is involved in tumor development and progression by promoting the migration and infiltration of monocytes and tumor-associated macrophages (TAMs)." (PMID 33213491, 2020).
tumor (continued). "We indeed found CCL2 showed low expression in normal colorectal tissues but tumor tissues as well as loss function of HOTAIR or overexpression of miR-206 would repress the activation of CCL2." (PMID 32489462, 2020). "Specifically, CCL2-secreting CAFs recruit tumor-associated macrophages, while CXCL12-secreting CAFs activate other immune components as mast cells, eosinophils, innate lymphoid cells, and helper T cells." (PMID 32668821, 2020). "These researchers suggested that the underlying mechanism involves chemokines such as CCL2, which are produced by cancer cells and, promote the recruitment of peripheral monocytes to the tumor microenvironment." (PMID 32993594, 2020). "CDDO-Me treatment redirects the TAM transcriptional profile, inducing signaling pathways associated with immune stimulation, and inhibits TAM tumor infiltration, consistent with decreased expression of CCL2." (PMID 32300202, 2020). "Wnt5a pro-tumour activity was found to be associated with the overexpression of the C-C motif chemokine ligand 2 (CCL2) in Wnt5a-treated macrophages." (PMID 33080952, 2020). "In this context, a recent report has demonstrated that NF-κB-mediated upregulation CCL2 (an agonist for CCR1/2/3) promotes tumor-associated macrophage infiltration and tumorigenesis in lung cancer." (PMID 33257678, 2020). "In a murine model of glioblastoma multiforme, both M-MDSCs and Tregs were recruited by CCL2 produced by tumor-associated macrophages (TAMs) and microglia." (PMID 32793192, 2020). "To evaluate the association of CCL2 and TAMs in esophageal carcinogenesis, we firstly determined the distribution of CCL2 with human tumor tissue microarrays constructed from ESCC patients (cohort I)." (PMID 32103760, 2020). "CCL2 is responsible for the accumulation of the tumor associated macrophages (TAMs) within the tumor environment, which secrete IL-8." (PMID 32886667, 2020). "Some tumor cells also express CCL2, and high-CCL2 expression is associated with tumor cell therapy resistance." (PMID 31611552, 2019). "Mechanistically, PIPKIγ facilitated PI3K-Akt-mTOR signaling pathway activation to increase STAT3 phosphorylation levels, thus triggering CCL2 transcription to enhance tumor-associated macrophage recruitment." (PMID 31781676, 2019). "Within the tumor, CCL2 polarizes M0-macrophages into Gas6-secreting M2-tumor-associated macrophages (M2-TAMs)." (PMID 31844158, 2019). "Further, by inhibiting transcription in the tumour associated macrophages, lurbinectedin downregulates immune-suppressive cytokines such as interleukin-6 (IL-6), interleukin-8 (IL-8), C-C motif chemokine 2 (CCL2) and VEGF." (PMID 31619019, 2019). "Tumor associated neutrophils (TAN) provide an important source of CCL2 in HCC and can act synergistically with TAM to support liver tumor progression." (PMID 31068952, 2019). "The most relevant transcription factor of CCL-2 is nuclear factor-κB (NFκB), which main role is associated with prevention of tumor cells, from apoptosis." (PMID 30680411, 2019). "CAF secretion of CXCL12/SDF1, M-CSF/CSF-1, IL-6, and CCL2/MCP-1 recruits tumor-associated macrophages (TAM) to the TME and actively differentiates TAMs into an M2 immunosuppressive phenotype." (PMID 31058816, 2019). "In a murine liver tumor model, tumor-associated fibroblast-secreted CCL2 induces mobilization and migration of MDSCs to the PMN through chemokine receptor 2 (CCR2)." (PMID 30792719, 2019). "CAF also secrete a lot of chemokine ligands (CXCL12/SDF1, CXCL14, CCL2, and others) that promote the proliferation of cancer cells and encourage the recruitment of tumor-associated macrophages, thereby contributing to immunosuppression." (PMID 30871158, 2019). "CCL2 is a powerful chemotactic protein for macrophages and tumor-associated macrophages (TAMs), which infiltrate into tumors and contribute to cancer progression via immune suppression." (PMID 30871130, 2019).
tumor (continued). "In contrast, Lavender reported that while in vitro delivery of CCL2 to 4T1 TENs enhanced the killing of the less aggressive 67NR variant of 4T1 tumor cells, intranasal delivery of CCL2 enhanced the seeding and outgrowth of tumor cells in the lung." (PMID 30873179, 2019). "The mRNA expression levels of CTRP1 were positively associated with the tumor-infiltrating macrophages and CCL2 in GBM (P<0.05, respectively)." (PMID 31183364, 2019). "The direct or indirect targeting effects exerted by miRNAs on VEGFA and CCL2 significantly reduced lung tumour angiogenesis, tumour-associated macrophages (TAMs) accumulation, tumour growth, and metastasis in mice." (PMID 30944831, 2019). "This was associated with decreased cytokine production including CCL2 leading to reduced tumor infiltration of tumor supporting monocytes and MDSCs." (PMID 31333662, 2019). "N2 neutrophils induce immunosuppression in the tumor microenvironment and have a number of associated markers, including CC-chemokine ligand 2 (CCL2), CCL5, neutrophil elastase (NE), cathepsin G, and a higher expression of arginase." (PMID 31695802, 2019). "More recently, HOTAIR has been implicated in maintaining HCC tumor microenvironment via HOTAIR-induced C–C motif chemokine ligand 2 (CCL2) expression." (PMID 31056726, 2019). "Together suggest S100A4 re-activate GemOE cells to secrete CCL2 that attracts macrophages and polarizes them into Gas6-secreting M2-tumor-associated macrophages (M2-TAMs42, 47, 48)." (PMID 31844158, 2019). "This is also observed in the development of lung cancer, with reduced frequency of tumor-associated macrophages which produce Arg1, CCL2, IL-10, and TGF-β." (PMID 29867925, 2018). "Enhanced levels of CCL2 in a variety of tumors were associated with cancer progression and increased tumor growth." (PMID 29751565, 2018). "Another component of the tumor microenvironment are the tumor-associated macrophages (TAMs) which are monocytes recruited by cytokines (such as the chemokine (C-C motif) ligand 2 [CCL2]) from the peritumoral tissues or bone marrow." (PMID 30134816, 2018). "Some examples include TGF- α/β guiding tumor-adipose cell interactions and CCL2/5 for tumor-tumor-associated macrophage interaction." (PMID 29881724, 2018). "Tumors become infiltrated with BM-DMs that are attracted to the tumor via the secretion of damage associated molecular patterns (DAMPs) and specific macrophage chemoattractants CSF-1 and chemokine C-C motif ligand 2 (CCL2)." (PMID 30356656, 2018). "IL-1β generated by tumor cells and by tumor-associated macrophages in an autocrine manner induced CCL2 secretion which in turn attracted macrophages." (PMID 29983861, 2018). "Tumor-associated macrophages (TAMs) are macrophages that are recruited to the TME by chemokines such as CCL2 (MCP-1) and CCL5 (RANTES)." (PMID 29652813, 2018). "As has been observed in other cancer models, lung tumor expression of CCL2 is associated with tumor growth in bone which likely mediated via an increase in OCL maturation." (PMID 29930538, 2018). "CCL2 is one of the major triggers of tumor-associated macrophage (TAMs) infiltration within the tumor microenvironment." (PMID 30126117, 2018). "In studies surveying neoplasm pathology, CCL2 levels are positively associated with tumor-associated Mφ that typically exhibit an M2-like phenotype." (PMID 29046677, 2017). "CCL2 secreted by GBM cells binds to its receptor on CCR4+ cells to cause them to migrate to the tumor microenvironment and surround the GBM (Ti-CCR4 cells)." (PMID 29312296, 2017). "The effect of CCL2 on tumor growth and metastasis has been linked to its role in the recruitment of pro-tumor or anti-tumor leukocytes into the tumor microenvironment." (PMID 28143493, 2017). "As a potential cancer therapy, IL-12p70 reversed the immunosuppressive phenotype of tumor-associated macrophages in a subcutaneous murine model, with concomitant reduced synthesis of CCL2 and IL-10." (PMID 28966800, 2017).